CSK (C-terminal Src kinase)
Diseases named in the same sentence as CSK in open-access papers (continued):
Sharing a sentence is not in itself a finding about the gene and the disease.
Autoimmunity (5 papers, 2013 to 2022). The occurrence of an immune reaction against the organism's own cells or tissues. "Since the T allele binds less efficiently to CSK than the C allele, C1858T T lymphocytes are indeed hyperresponsive and predispose harboring individuals to autoimmunity." (PMID 35355982, 2022). "This polymorphism changes to a Trp the Arg620 that is essential for LYP binding to CSK, suggesting that a change in the association between these proteins will contribute to the generation of autoimmunity." (PMID 23359562, 2013). "PTPN22 interacts with CSK, and this interaction is relevant for PTPN22 function, as shown by the fact that a human PTPN22C1858T variant, encoding an amino acid R620W substitution which impairs its interaction with CSK, is associated with increased risk of autoimmunity." (PMID 33425916, 2020). "Because of that, in an attempt to establish if PTPN22/CSK is actually involved in HSP, we analyzed two well-known CSK and two functional PTPN22 polymorphisms, previously associated with autoimmunity, in the largest series of Caucasian patients with this vasculitis ever assessed for genetic studies." (PMID 26458874, 2015). "Furthermore, PTPN22 binds to C-Src tyrosine kinase (CSK) forming a key complex in autoimmunity." (PMID 28874816, 2017). "Two well-known CSK (CSK rs34933034 and CSK rs1378942) and two functional PTPN22 (PTPN22 rs2476601 (R620W) and PTPN22 rs33996649 (R263Q)) polymorphisms, previously associated with autoimmunity, were genotyped with TaqMan single nucleotide polymorphism (SNP) genotyping assays." (PMID 26458874, 2015). "Therefore, to determine how the R620W polymorphism modifies the function of this complex and contributes to the induction of autoimmunity, in this work we have analyzed LYP/CSK interaction and its relevance for TCR signaling." (PMID 23359562, 2013).
gastric cancer (5 papers, 2012 to 2025). A primary or metastatic malignant neoplasm involving the stomach. "For instance, the loss of CSK or PTEN function in HER2-amplified gastric cancer cell lines, such as NCI-N87 and OE19, leads to lapatinib resistance in these cancer cells." (PMID 41340127, 2025). "Because some CagA interacting molecules such as SHP-2, CRK and CSK are only able to respond with phosphorylated CagA, SRC can be more important in influencing other's cellular functions and inducing development of gastric cancer." (PMID 22383989, 2012).
ovarian carcinoma (5 papers, 2011 to 2021). A malignant neoplasm originating from the surface ovarian epithelium. "In summary, these results show that CSK is an epigenetically regulated gene with demethylation leading to higher gene expression, both in ovarian cancer PDX models as well as in cell lines." (PMID 27765068, 2016). "Thus, more in-depth functional validation of CSK is warranted to study how this protein is involved in chemoresponses and OS of ovarian cancer patients." (PMID 27765068, 2016). "Moreover, an inverse correlation (r = −0.612, p < 0.0021) between methylation and gene expression of CSK was found in the ovarian cancer cell lines." (PMID 27765068, 2016). "Therefore, it is tempting to speculate that reversion of epigenetically silenced CSK or induction of CSK expression in ovarian cancer might lead to an adequate suppression of Src family kinases and consequently less tumor growth." (PMID 27765068, 2016). "In particular, the C-terminal Src kinase (CSK) gene was successfully validated for epigenetic regulation in different PDX models and ovarian cancer cell lines." (PMID 27765068, 2016).
systemic lupus erythematosus (5 papers, 2015 to 2024). An autoimmune multi-organ disease typically associated with vasculopathy and autoantibody production. "These abnormalities are probably related to the dysregulation of IRF7 and CSK genes which are the key lupus susceptibility genes." (PMID 31370803, 2019). "Polymorphisms in CSK have been linked to both SSc and systemic lupus erythematosus (SLE) and are associated with aberrant B cell signaling." (PMID 25569146, 2015). "The tyrosine-protein kinase CSK has been associated with systemic lupus erythematosus (SLE)." (PMID 36578781, 2022). "In accordance with that, some studies have described an association between two well-known genetic variants located in the CSK gene (CSK rs34933034 and CSK rs1378942) and several immune-mediated disorders such as systemic lupus erythematosus and systemic sclerosis in Caucasian patients." (PMID 26458874, 2015).
colorectal cancer (3 papers, 2013 to 2022). A primary or metastatic malignant neoplasm that affects the colon or rectum. "However, the extent and exact mechanism of how CSK contributes to tumor suppression is being disputed, because of the following reasons: 1) CSK extracted from colorectal cancer cells remains functional in terms to its SFK inhibition when tested in vitro." (PMID 36578781, 2022). "Interestingly, this recruitment step is impaired in colorectal cancer, resulting in retention of CSK in the cytoplasm." (PMID 26087188, 2015). "However, increased CSK expression along with SFK activity has been observed in primary carcinoma and human colorectal cancer cell lines, indicating that CSK-dependent regulation of SFK signaling may be specific to some cancers." (PMID 26087188, 2015).
Arrhythmia (2 papers, 2016 to 2025). Any cardiac rhythm other than the normal sinus rhythm. "Specifically, the inhibition of C-terminal Src kinase (CSK) and alterations in the inositol phosphoinositide 3-kinase (PI3K)-Akt signaling pathway, along with possible disruptions in cardiac ion channels, are thought to contribute to the development of arrhythmias and atrial fibrosis." (PMID 40933891, 2025).
rheumatoid arthritis (2 papers, 2017 to 2023). A chronic, systemic autoimmune disorder characterized by inflammation in the synovial membranes and articular surfaces. "Finally, several genes (SEMA7A, CSK, GUCY1A2, EMCN, OPRM1) are associated with rheumatoid arthritis (RA)." (PMID 36658473, 2023).
acute megakaryoblastic leukemia (1 paper, 2021). Acute megakaryoblastic leukemia (AMKL) is a form of acute myeloid leukemia (AML) that occurs predominantly in childhood and particularly in children with Down syndrome (DS-AMKL). "MATK encodes megakaryocyte-associated tyrosine kinase, which is structurally similar to C-terminal Src kinase; notably, megakaryocyte-associated tyrosine kinase is associated with acute megakaryoblastic leukemia." (PMID 34912812, 2021).
Behçet’s disease (1 paper, 2015). "In this regard, an implication of PTPN22/CSK in the susceptibility to giant cell arteritis, Behçet’s disease and ANCA-associated vasculitides has been described in Caucasians." (PMID 26458874, 2015). "In line with that, although the genetic influence of PTPN22/CSK in several vasculitides (such as giant cell arteritis, Behçet’s disease and antineutrophil cytoplasmic antibody (ANCA)-associated vasculitides) has been demonstrated, there is scarce information on the role of PTPN22/CSK in HSP." (PMID 26458874, 2015).
colitis (1 paper, 2023). Inflammation of the colon. "In a model of inflammatory bowel disease based on dextran sodium sulfate (DSS) induction, increased susceptibility to colitis has been shown in IEC-specific CSK-deficient mice." (PMID 37397251, 2023). "Mechanistically, this CSK-dependent pathogenesis of DSS-induced colitis involves activation of Src in the absence of CSK, which followed by the phosphorylation and subsequent proteasomal degradation of occludin, leads to the increased intercellular permeability of the IECs." (PMID 37397251, 2023).
dementia (1 paper, 2024). Loss of intellectual abilities interfering with an individual's social and occupational functions. "Four protective proteins (PLEK, DAPP1, CSK and CASP3) that decreased postinfection in the BLSA were significantly decreased in dementia cases in the ARIC study, with several other protective proteins (EIF4A1, DSG1, PIK3CG, PRKCB and LYN) showing similar trends." (PMID 39143319, 2024).
epilepsy (1 paper, 2022). A brain disorder characterized by episodes of abnormally increased neuronal discharge resulting in transient episodes of sensory or motor neurological dysfunction, or psychic dysfunction. "However, no studies regarding CSK’s role in these diseases have been published so far and further research is needed to determine CSK’s contribution to neurodegeneration and epilepsy." (PMID 36578781, 2022).
Ewing sarcoma (1 paper, 2020). A small round cell tumor that lacks morphologic, immunohistochemical, and electron microscopic evidence of neuroectodermal differentiation. "Conversely, the expression of Src with a mutation in the CSK phosphorylation site (Y530F), which evades inactivation by CSK, inhibited Ewing sarcoma growth." (PMID 33147457, 2020). "This suggests that endogenous GDF6 stimulates the interaction between CD99 and CSK in Ewing sarcoma." (PMID 33147457, 2020). "Furthermore, CSK silencing in Ewing sarcoma resulted in activation of Src, induction of p21, and growth arrest." (PMID 33147457, 2020). "Inhibition of cell migration by GDF6 silencing was abolished by dominant-negative Src and by CSK, suggesting that GDF6 silencing inhibits Ewing sarcoma migration through hyperactivation of Src." (PMID 33147457, 2020).
follicular lymphoma (1 paper, 2021). Follicular lymphoma is a form of non-Hodgkin lymphoma characterized by a proliferation of B cells whose nodular structure of follicular architecture is preserved. "We also treated the CSK- and PTEN-null OE19 cells with the PI3K inhibitor copanlisib (BAY 80–6946), a drug approved by the FDA for patients with relapsed follicular lymphoma." (PMID 34399705, 2021).
leprosy (1 paper, 2023). Leprosy is a chronic infectious disease affecting primarily the skin and peripheral nervous system. "Thus, the leprosy susceptibility loci, including NOD2, RIPK2, TNFSF15, LACC1, LRRK2, IL12B, and HLA‐DR in phagocytes and IL23R, TYK2, and CSK in T cells, may interfere with the synergistic antimicrobial response between phagocytes and T cells." (PMID 38020709, 2023).
lung carcinoma (1 paper, 2025). "To further verify the role of these prognostic genes in AML, we performed in vitro experiments on PTPN6 and CSK which their cellular effects in lung cancer are unclear." (PMID 40255396, 2025).
meningioma (1 paper, 2025). A generally slow growing tumor attached to the dura mater. "Additionally, there were eight kinases that were not significantly differently expressed between meningioma and VS present in the macrophages (LCK, PDGFRB, FGFR1, FLT1, CSK, MEK, MAP2K2, and ERBB2)." (PMID 41437121, 2025).
migraine (1 paper, 2024). "We further found drugs targeted for another six proteins (CSK, FER, GP1BA, PLCG1, PLG, and SERPING1), although currently there are no indications for migraine." (PMID 38898596, 2024).
Neonatal sepsis (1 paper, 2025). Systemic inflammatory response to infection in newborn babies. "In summary, transcriptomic profiling has uncovered key immune pathways involved in neonatal sepsis, including T-cell receptor signaling (CD3G), leukocyte chemotaxis (CXCL10, CSK), inflammatory activation (MM8, NF-κB1A), and IFN-1-mediated immune modulation." (PMID 40927580, 2025).
non-small cell lung carcinoma (1 paper, 2024). A group of at least three distinct histological types of lung cancer, including non-small cell squamous cell carcinoma, adenocarcinoma, and large cell carcinoma. "When the KRas-CSK biosensors were transfected in human normal BEAS-2B lung epithelial cells and human A549 non-small cell lung cancer cells, we found that the ECFP/FRET ratio in these two cell types was within 0.35~0.5." (PMID 38667199, 2024).
pancreatic cancer (1 paper, 2023). "Indeed, activation of Src via CSK downregulation increases cell proliferation and angiogenesis in pancreatic cancer." (PMID 37519303, 2023). "In pancreatic cancer cells, CSK inhibition using the inhibitor ASN2324598 substantially decreases Y527 phosphorylation in Src, resulting in increased proliferation and activation of pro-oncogenic pathways, such as MAPK/MEK, and pro-angiogenic growth factors, like VEGF." (PMID 37519303, 2023).
viral infections (1 paper, 2024). "In addition, C-terminal src kinase (CSK) phosphorylates STING at tyrosine residues (Tyr240 and Tyr245) to promote its aggregation and immune response activation during viral infections, such as herpes simplex virus 1 (HSV-1)." (PMID 39669992, 2024).
cancer (39 papers, 2009 to 2025). A tumor composed of atypical neoplastic, often pleomorphic cells that invade other tissues. "CSK can also localise directly in focal adhesions via adapter proteins, causing reorganisation of integrins and impacting cancer progression." (PMID 37519303, 2023). "The genes BLK, CDC247, CSK, IRF5, STAT1, STAT4, and TNIP1 are associated with AIDs, and CDC37, DDX6, HSPA6, MAPT, PPIB, STAT1, and STAT4 are associated with cancers." (PMID 40429780, 2025). "After stimulation with EGF, the CSK protein’s activity was also different, but the activity of the CSK protein in A549 cancer cells was significantly higher than that of normal BEAS-2B cells." (PMID 38667199, 2024). "CSK is a negative regulator of Src, so we further investigated the expression of the CSK kinase in cancer cells." (PMID 38667199, 2024). "With CSK as the major negative regulator of SFKs, one would assume CSK downregulation plays an important role in activation of SFKs in most cancer cells." (PMID 37397251, 2023). "Even though SFK oncogenic signalling has been extensively described before, the specific role of CSK and its crosstalk with integrins in cancer progression, for example, in mechanosensing, remain veiled." (PMID 37519303, 2023). "In the next sections we will discuss integrin function, the crosstalk between integrins and SFKs relevant for cancer progression, and finally, how CSK can regulate integrin functions in cancer through the modulation of SFK signalling." (PMID 37519303, 2023). "In the next section, we will revise how CSK interacts with SFKs and expand how CSK-dependent inhibition of SFKs can impact integrin signalling in cancer." (PMID 37519303, 2023). "CBP, a scaffolding protein involved in recruiting CSK to the membrane, is downregulated in several types of cancer cells, contributing to SFK activation." (PMID 37519303, 2023). "This evidence showed that Src and CSK play an important role in the regulation of skin inflammation and cancer development." (PMID 36983027, 2023). "This article aims to review recent advances in our understanding of integrin signalling and the role of SFKs and CSK in cancer progression." (PMID 37519303, 2023). "Dysregulation of CSK localisation can contribute to oncogenic activity of SFKs, leading to cancer cell invasion and tumour formation." (PMID 37519303, 2023). "Lastly, as a key member of the Src family kinases (SFKs), CSK plays a vital role in combating cancer progression in various cancers." (PMID 38304232, 2023). "Lastly, a functional genomics screen with human prostate cancer cells identified a subclass of cancer in which simple downregulation of CSK levels affected oncogenic properties of the cells." (PMID 37397251, 2023). "While CSK has shown promising results in reducing tumour growth and metastatic potential in cancer models, further research is needed to fully understand its potential as a cancer therapeutic target." (PMID 37519303, 2023). "In this line, elevated expression of CSK in human cancer cell lines appears to correspond to elevated c-Src protein-tyrosine kinase activity, for example, CSK is widely expressed in HT-29 and SW620 cells that contain high levels of active c-Src53,54." (PMID 37848415, 2023). "CSK is known to activate Src via phosphorylation of the Tyr527 residue related to anti-cancer effects." (PMID 36983027, 2023). "While CSK displays antioncogenic activity in some cancers by inactivation of SFKs, this mechanism is impaired in CRC." (PMID 35740644, 2022). "On the other hand, in human cancer, CSK activity can be prevented through a complex epigenetic mechanism via delocalization from the plasma membrane." (PMID 32717909, 2020). "Although CSK was initially thought to act as a tumor suppressor, its contribution to cancer remains less clear." (PMID 26087188, 2015). "The dysfunction of CSK in normal cells promotes the development of cancer." (PMID 38667199, 2024).